SPHK1 (sphingosine kinase 1)
Diseases named in the same sentence as SPHK1 in open-access papers (continued):
Sharing a sentence is not in itself a finding about the gene and the disease.
rheumatoid arthritis (9 papers, 2013 to 2025). A chronic, systemic autoimmune disorder characterized by inflammation in the synovial membranes and articular surfaces. "The pathogenesis of rheumatoid arthritis (RA) is complex, with the SphK1/S1P signaling pathway playing a crucial role." (PMID 40606620, 2025). "We found that sphingosine kinase-1, which regulates S1P production is increased at inflamed sites in mice and in patients with the chronic inflammatory disease, rheumatoid arthritis." (PMID 29225602, 2017). "and Jaspis. sp., and in an in vivo rat model of complete Freund’s adjuvant rheumatoid arthritis (RA), showed it acted as a SphK1 inhibitor in vitro and significantly improved RA symptoms measured by decreased pro-inflammatory cytokines TNF-α, IL-6, and IL-1β, swelling volume, and arthritis score." (PMID 39057418, 2024). "It is noteworthy that the SphK1/S1P signaling pathway plays a significant role in the pathogenesis of rheumatoid arthritis (RA)." (PMID 40606620, 2025). "Furthermore, we show that sphingosine kinase-1 (SPHK1), one of the enzymes responsible for the conversion of sphingosine into S1P, is increased at sites of acute inflammation in mice and in the inflamed synovium of rheumatoid arthritis (RA) patients." (PMID 29225602, 2017).
atherosclerosis (8 papers, 2017 to 2025). A disease characterized by the build-up of fatty material and calcium deposition in the arterial wall resulting in partial or complete occlusion of the arterial lumen. "These pieces of evidence suggest that SphK1 promotes vascular inflammation and expression of endothelial cell adhesion molecules, which are closely associated with atherosclerosis preformation." (PMID 39920588, 2025). "Transgenic overexpression of SphK1 in SphK2-deficient mice rescued aggravation of atherosclerosis and abnormalities of autophagosomes and lysosomes in macrophages with reductions of sphingosine, suggesting at least partial overlapping actions of two SphKs." (PMID 31797978, 2019). "Sphk1 overexpression in Sphk2-deficient mice rescues aggravated atherosclerosis." (PMID 39899071, 2025). "SPHK1, the key enzyme in S1P metabolism, is involved in various biological processes, including inflammation, atherosclerosis, and angiogenesis." (PMID 37432552, 2023). "TNF-α rapidly activates SphK1 in monocytes leading to the expression of adhesion factor, which has been shown to play a key role in the early stages of atherosclerosis pathogenesis." (PMID 34737701, 2021). "In the present study, the effects of genetic deletion of Sphk2 and Sphk1 on atherosclerosis were clearly different." (PMID 31797978, 2019). "SphK1 and SphK2 have distinct, isoform-specific roles in atherosclerosis." (PMID 39920588, 2025). "Sphk1 inhibition with SKI-II exacerbates atherosclerosis in mice." (PMID 39899071, 2025). "SphK1 deficiency abrogated cellular MCP-1 production when microvascular endothelial cells from Sphk1-deficient mice were treated with a protease-activated receptor 1-activating peptide, suggesting that SPHK1 inhibition is a novel therapeutic approach for atherosclerosis." (PMID 39920588, 2025). "However, it is possible that SphK1 and SphK2 have distinct, isoform-specific roles in atherosclerosis." (PMID 31797978, 2019). "For example, reduction of S1P levels through inhibition of sphingosine kinase 1 increases atherosclerosis development, while elevation of S1P levels through selective inactivation of S1P lyase in hematopoietic cells protects against atherosclerosis." (PMID 29244772, 2017). "In Western diet (WD)-fed Sphk1−/− mice and Sphk2−/− mice, both with an ApoE-deficient background, the exacerbation of atherosclerosis in mice lacking Sphk2, but not Sphk1, was attributed to impaired autophagic degradation of lipid droplets (LDs) in macrophages." (PMID 39920588, 2025). "Nonetheless, aggravated atherosclerosis is observed in Sphk2- and not Sphk1-deficient mice." (PMID 39899071, 2025). "We assessed whether SphK1 overexpression can rescue atherosclerosis in Sphk2−/− mice." (PMID 31797978, 2019). "In this study, we analysed atherosclerosis in Western diet (WD)-fed Sphk1−/− mice and Sphk2−/− mice, both with an ApoE-deficient background and found that Sphk2−/− mice, but not Sphk1−/− mice, show aggravation of atherosclerosis because of defective autophagic breakdown of LDs in macrophages." (PMID 31797978, 2019). "Researchers have speculated that BC294640 targets SphK1 and SphK2 at different concentrations; nonetheless, it is possible that both isoforms were not equally suppressed during treatment, thereby explaining the bidirectional regulatory effect of SphKs on atherosclerosis." (PMID 39920588, 2025).
esophageal cancer (8 papers, 2011 to 2025). A primary or metastatic malignant neoplasm involving the esophagus. "In esophageal cancer, high expression of SPHK1 is associated with poor 5-year overall survival (OS), and elevated SPHK1 levels are significantly correlated with metastatic lymph node status." (PMID 41304867, 2025). "Overexpression of SphK1 is closely associated with the invasion and metastasis of esophageal carcinoma." (PMID 34831211, 2021). "Because both EGF and AREG have been implicated in progression of esophageal cancer, it was of interest to examine the involvement of SPHK1." (PMID 21936950, 2011). "By Kaplan-Meier analysis, strong SPHK1 expression was significantly associated with clinical failure (P < 0.01), suggesting the involvement of SPHK1 in aggressiveness of human esophageal carcinoma." (PMID 21936950, 2011). "Interestingly, in esophageal cancer, the high expression of SPHK1 is associated with poor 5-year OS and increased SPHK1 levels are significantly correlated with LN metastasis; therefore, SPHK1 is a potential biomarker for outcome prediction in clinical practice." (PMID 35965565, 2022). "Since SphK1 protein expression, measured by western blotting, has been found to correspond to EGFR phosphorylation in esophageal cancer cell lines, we also examined the relationship between SphK1 and pEGFR IHC staining." (PMID 28778177, 2017). "We identified sphingosine kinase 1 (SPHK1) as an invasion and metastasis-related gene of esophageal cancer." (PMID 21936950, 2011). "Our report is the first to implicate the involvement of SPHK1 in the metastasis of esophageal cancer." (PMID 21936950, 2011). "SPHK1 protein was found to be overexpressed in seven of the twelve (58%) esophageal carcinoma tissues; that is, SPHK1 expression was higher in the tumor tissue than in the companion normal tissue." (PMID 21936950, 2011). "Exogenous expression of SPHK1 in vitro and in vivo further showed that it is a key factor in esophageal carcinoma cell invasion." (PMID 21936950, 2011). "Through this analysis, we identified sphingosine kinase 1 (SPHK1) as one such gene that participates in esophageal carcinoma invasion and metastasis." (PMID 21936950, 2011). "Esophageal carcinoma tissue microarray analysis indicated that SPHK1 expression correlated with the depth of tumor invasion (P < 0.0001) and lymph node metastasis (P = 0.016)." (PMID 21936950, 2011). "We then evaluated the expression of SPHK1 protein in an esophageal carcinoma tissue microarray (n = 274 tissue microarray elements from 124 cases of esophageal squamous carcinoma)." (PMID 21936950, 2011). "By Western blotting, in 7/12 cases (58%), SPHK1 expression was higher in esophageal carcinomas than in the companion normal tissue." (PMID 21936950, 2011). "We have established an esophageal carcinoma invasion model and generated a highly invasive tumor cell subline in which SPHK1 was overexpressed." (PMID 21936950, 2011). "SPHK1 expression was analyzed by RT-PCR and immunofluorecence in esophageal carcinoma cell lines, including KYSE30, KYSE150, KYSE510, KYSE2, EC9706, and NEC cells." (PMID 21936950, 2011). "SphK1 may enhance cell invasion and metastasis in esophageal carcinoma by regulating the phosphorylation of EGFR." (PMID 34831211, 2021). "In summary, our data implicate SPHK1 in the metastasis of esophageal cancer." (PMID 21936950, 2011). "Thus, modulating SPHK1 expression or activity is an attractive additional therapeutic strategy for treatment of esophageal cancer and perhaps other cancers as well." (PMID 21936950, 2011). "Our study also identified downstream mediators of SPHK1 in esophageal cancer cells that may mediate enhanced malignant behavior, and several of these mediators may be useful as therapeutic targets." (PMID 21936950, 2011). "Further investigation revealed SPHK1 was significantly correlated with esophageal cancer invasion and metastasis and may be a valuable prognostic marker." (PMID 21936950, 2011).
esophageal cancer (continued). "We therefore examined whether expression of the SPHK1 protein could be used to predict clinical outcome in esophageal carcinoma patients with available survival information." (PMID 21936950, 2011). "We observed the overexpression of SPHK1 transcripts in esophageal carcinoma and identified downstream mediators that may mediate enhanced malignant behavior in these tumor cells." (PMID 21936950, 2011).
head and neck cancer (8 papers, 2013 to 2025). A primary or metastatic malignant neoplasm affecting the head and neck. "Results of recent studies identify SphK1 as a potential modulator of carcinogenesis in head and neck cancer." (PMID 24970177, 2013). "Whether SphK1 is directly involved in activation of EGFR in head and neck cancer is unknown." (PMID 24970177, 2013).
inflammatory bowel disease (8 papers, 2013 to 2022). A spectrum of small and large bowel inflammatory diseases of unknown etiology. "In addition, Sphk-1 and S1P have been demonstrated as important inflammatory mediators in asthma, rheumatoid arthritis and inflammatory bowel disease (IBD)." (PMID 23817990, 2013). "The role of SphK1 activity in mediating the TNF-α-induced decrease in IL-10 as well as the decrease in TNF-α itself has important translational implications in other inflammatory disorders, particularly those associated with autoimmune diseases such as inflammatory bowel disease." (PMID 35409108, 2022).
myocardial infarction (8 papers, 2017 to 2024). Gross necrosis of the myocardium, as a result of interruption of the blood supply to the area, as in coronary thrombosis. "Another study confirmed that the SphK1/S1P/S1PR1 signaling pathway activates the proinflammatory response after myocardial infarction." (PMID 37238688, 2023). "In addition, they found that the upregulation of SphK1 and S1PR1 caused an increase in cardiac S1P after myocardial infarction, while the SphK1 inhibitor inhibited S1P and improved cardiac insufficiency." (PMID 37238688, 2023). "This study sought to evaluate the mechanism through which SPHK1 might influence ER stress during myocardial infarction (MI)." (PMID 37773702, 2023). "Conversely, significant increases in cardiac S1P, SphK1 and S1PR1 are observed in postmyocardial infarction (MI) associated with the proinflammatory response, and inhibition of this inflammatory pathway may benefit patients with MI." (PMID 33003377, 2020).
thyroid cancer (8 papers, 2013 to 2022). "In clinical samples, overexpression of SphK1 correlated significantly with the expression of PCNA, suggesting a strong association between SphK1 overexpression and proliferation of thyroid cancer cells." (PMID 24970169, 2013). "Furthermore, the expression of SphK1 correlated significantly with the expression of proliferating cell nuclear antigen (PCNA), indicating that proliferation of thyroid cancer cells is associated with the expression of SphK1." (PMID 24970169, 2013). "MicroRNA-128 targets SPHK1 to induce apoptosis and reduce cell proliferation, migration in thyroid cancer cell lines, and inhibits tumor growth." (PMID 33113852, 2020). "In our studies, overexpression of SphK1 in follicular ML-1 and FTC-133 thyroid cancer cells resulted in a decreased proliferation, compared with mock-transduced cells or cells transduced with the inactive G82D mutant of SphK1." (PMID 24970169, 2013). "More specifically, 69% (29 out of 42) of thyroid cancer samples analyzed elicited SphK1 overexpressed as measured with IHC." (PMID 24970177, 2013). "shRNA targeted knockdown of SphK1 resulted in reduced proliferation, and the number of floatage-independent colonies in thyroid cancer cell lines WRO (follicular), FRO (anaplastic), and S579 (poorly differentiated cancer with feature of papillary cancer)." (PMID 24970177, 2013). "As seen in HNSCC, SphK1 is overexpressed in human thyroid cancer and expression levels correlate with the degree of malignancy." (PMID 24970177, 2013). "shRNA targeting SphK1 in thyroid cancer cells resulted in a cascade potentially increasing cell motility." (PMID 24970177, 2013). "The use of similar models and continuity in these studies elucidate that SphK1 regulates migration in thyroid cancer via a S1P-PKCα-ERK1/2 pathway." (PMID 24970177, 2013). "Clearly, more investigations are needed to clarify if inhibition of SphK1 or S1P-receptors will be of clinical significance in the treatment of thyroid cancer." (PMID 24970169, 2013). "Taken together, these studies demonstrate that SphK1 is overexpressed in thyroid carcinoma, and SphK1/S1P is critical in regulating migration." (PMID 24970177, 2013). "Moreover, blockade of SphK1 inhibited growth in several tumour types, including breast, colon and thyroid cancer." (PMID 33931106, 2021). "This next section reviews studies that describe SphK1’s role in thyroid cancer." (PMID 24970177, 2013). "However, reports studying SphK1 in thyroid cancer provide valuable information and will be discussed when relevant." (PMID 24970177, 2013). "Research in thyroid cancer has identified that ERK1/2 and PKC is responsible for modulating SphK1/S1P-stimulated migration." (PMID 24970177, 2013). "For example, previous research has shown that SphK1 is overexpressed in HNSCC tumors, and esophageal and thyroid carcinomas." (PMID 24970177, 2013). "S1P is known to stimulate cell proliferation and migration in human aortic endothelial cells, murine satellite cells, WiT49 cells, human thyroid cancer cells, and many other cell types and can be inhibited by SPHK I2 which is a selective inhibitor of SphK1 with anti-proliferative capacity." (PMID 28806736, 2017).
adenoma (7 papers, 2011 to 2023). A neoplasm arising from the epithelium. "To investigate the role of SPHK1 in CD, we performed a heatmap analysis of key genes involved in phospholipid metabolism and signaling pathways in CD adenomas and surrounding normal tissues using the GEO dataset (GEO208107)." (PMID 38027207, 2023). "Our results show a significant over-expression of SphK1 mRNA and protein expression in the carcinomas compared with adenomas (P < 0.01 for all comparisons)." (PMID 26673009, 2016). "Concomitantly, epithelial cell proliferation in the polyps was attenuated, suggesting that SPHK1 regulates adenoma progression." (PMID 21936950, 2011). "Moreover, some studies showed that adenomas and cancers have higher expression levels of sphingosine kinase 1, which is responsible for the conversion of sphingosine into sphingosine-1-phosphate, compared to normal mucosa using human colon samples (47, –, 49)." (PMID 32071266, 2020). "Deletion of the SPHK1 gene in these mice resulted in reduction of adenoma size." (PMID 21936950, 2011). "Furthermore, the proportion of double-positive cells for SPHK1 and ACTH was significantly higher in the nonremission CD adenomas tissues than that in the remission CD adenomas." (PMID 38027207, 2023).
autoimmune disease (7 papers, 2016 to 2022). A disorder resulting from loss of function or tissue destruction of an organ or multiple organs, arising from humoral or cellular immune responses of the individual to their own tissue constituents. "With the important role of SphK1 in autoimmune diseases, neurological and cardiovascular diseases, and cancer gradually revealed, the design and development of SphK1 targeted drugs has become a research hotspot at home and abroad." (PMID 34737701, 2021). "Sphk1/S1P/S1PR signaling pathway can be used as a target for the treatment of autoimmune diseases." (PMID 34867796, 2021). "Previous studies have shown that SPHK inhibitors (FTY720, ABC294640, and PF-543) can regulate S1P by inhibiting SPHK-1/2 and maybe potential therapeutic drugs for autoimmune diseases." (PMID 35237148, 2021).
chronic myeloid leukemia (7 papers, 2015 to 2025). "Similarly, SPHK1 inhibition reduce BCR/ABL-induced upregulation of MCL-1 in chronic myeloid leukemia cells." (PMID 37020867, 2023). "Thus, overexpression of SphK1 in chronic myelogenous leukemia (CML) can increase resistance to the tyrosine kinase inhibitor imatinib by enhancing the stability of its target, the mutated kinase BCR-ABL." (PMID 35756630, 2022). "However, while SKIP has been shown to inhibit SPHK function in fibroblasts, a study in K562 Chronic Myelogenous Leukemia cells reported that SKIP acts more as a positive, rather than negative, regulator of SPHK1/S1P." (PMID 36361536, 2022). "In chronic myeloid leukemia (CML), an abnormally high expression of SPHK1 was shown to exacerbate the resistance to the imatinib drug." (PMID 40332322, 2025). "Similarly, overexpression of Sphk1 inhibits the activation of caspase 3, cytochrome c and SMAC/Diablo release from mitochondria through the modulation of Bim, Bcl‐XL and Mcl1 in chronic myeloid leukaemia cells." (PMID 25056275, 2015).
influenza (7 papers, 2020 to 2026). An acute viral infection of the respiratory tract, occurring in isolated cases, in epidemics, or in pandemics; it is caused by serologically different strains of viruses (influenzaviruses) designated A, B, and C, has a 3-day incubation period, and usually lasts for 3 to 10 days. "Sphk1 is a gene encoding for a kinase that controls cellular differentiation and apoptosis and serves as an important pro-viral factor by regulating the synthesis of viral RNA and export of the viral ribonucleoprotein complex upon infection with influenza." (PMID 37069680, 2023). "In cases of severe influenza infection, Sphk1 level and activity have been shown to be increased, promoting replication of influenza." (PMID 37069680, 2023). "In summary, the present results indicate that influenza virus infection induces Sphk1 gene expression in multiple tissues to elevate the level of circulating S1P at the lethal phase of severe influenza." (PMID 34635791, 2021). "Increased expression levels of Sphk1 in multiple tissues indicated the activation of S1P synthesis during influenza." (PMID 34635791, 2021).
ischemic stroke (7 papers, 2017 to 2025). A stroke disorder caused by obstruction of blood flow to the brain, due to thrombotic (local blood clot formation) or embolic (due to a blood clot or other material traveling from another site) event. "Thus, the UPRmt protects neural viability and mitochondrial homeostasis, and the Sirt3/Foxo3/Sphk1 pathway is a promosing therapeutic candidate for ischemic stroke." (PMID 37705748, 2023). "Suppression of the inflammation by targeting miR-19a/b-3p/SIRT1/FoxO3/SPHK1 could be a promising avenue to improve the outcome of ischemic stroke." (PMID 34051800, 2021). "In summary, our results offer novel evidence that endothelial Sphk1/S1P signaling regulates brain injury in the context of ischemic stroke in an eNOS‐ and NO‐dependent manner, suggesting that targeting this signaling axis may represent a viable therapeutic strategy for future treatment efforts." (PMID 31814336, 2020).